GPX4 (glutathione peroxidase 4)
Diseases named in the same sentence as GPX4 in open-access papers (continued):
Sharing a sentence is not in itself a finding about the gene and the disease.
ovarian carcinoma (continued). "Another study also shows that Erastin combined with cisplatin can increase the expression of ACSL4 and cyclooxygenase‐2 (COX‐2) and decrease the expression of GPX4 and FTH1 in HEY cells and ovarian cancer tissues, thus promoting ferroptosis in HEY cells and inhibiting tumor growth." (PMID 40821694, 2025). "Moreover, expression levels of both SLC7A11 and GPX4 were upregulated in platinum-resistant A2780/DDP and SKOV3/DDP cells compared with the platinum-sensitive A2780 and SKOV3 parental ovarian cancer cells." (PMID 38203758, 2024). "Thus, agrimonolide acts as an apoptosis- and ferroptosis-inducing agent in ovarian cancer cells and induces ferroptosis through the modulation of the SCD1/SLC7A11/GPX4 axis." (PMID 38203758, 2024). "Furthermore, the NRF2 downstream transcriptional target genes HO-1 and GPX4 were both upregulated, suggesting that NRF2 is involved in ovarian cancer metastasis." (PMID 38396022, 2024). "Based on these evidences, we hypothesized that simultaneous inhibition of both GPX4 and NRF2 may be an effective way to suppress ovarian cancer metastasis." (PMID 38396022, 2024). "Finally, analysis using a peripheral blood exosome database indicated that the contents of key factors (e.g., ATF4, GPX4, and ATG3) in peripheral blood exosomes from patients with ovarian cancer, were significantly higher than those of the healthy controls." (PMID 37215446, 2023). "Blocking SCD1/FADS2 contributed to increased cellular reactive oxygen species (ROS) and lipid peroxidation through downregulated glutathione peroxidase 4 (GPX4) and the reduced glutathione/oxidized glutathione (GSH/GSSG) ratio in ascites-derived ovarian cancer cells, thereby promoting ferroptosis." (PMID 37240297, 2023). "In addition, we performed exosome database screening and found that the levels of ATF4, GPX4, GSS, KEAP1, and ATG3 in the peripheral blood exosomes of patients with ovarian cancer were significantly higher than those from the healthy controls." (PMID 37215446, 2023). "The results from qRT-PCR and Western blot assays showed that both the mRNA level and protein expression of SNAI2, SLC7A11 and GPX4 in SKOV3, A2780 and CAOV3 cells were higher than that in IOSE-80, suggesting that SNAI2, SLC7A11 and GPX4 were upregulated in ovarian cancer." (PMID 35220872, 2022). "Considering the importance of SLC7A11 and GPX4 in ferroptosis, we speculated that SNAI2 might be involved in the regulation of ferroptosis, which accounted for its role in ovarian cancer." (PMID 35220872, 2022). "In parallel, GPX4 expression positively correlated with elevated ALDH1A1 levels in colon CSCs 53, and fluorescence-activated cell sorting (FACS) analysis revealed that SOD2 was upregulated in ALDH+ ovarian cancer cells." (PMID 31695757, 2019). "In addition, the expression of GPX4 and SLC7A11 in platinum‐resistant ovarian cancer cell lines SKOV3 and A2780 can be downregulated by supermagnetic nano‐iron oxide (SPIO) human serum, which can increase the level of ROS in cells and induce ferroptosis in cancer cells." (PMID 40821694, 2025). "Previous studies have found that ferroptosis is involved in the regulation of platinum‐resistant ovarian cancer cells, and the survival of the platinum‐resistant cell population marked by frizzled transmembrane receptor 7 (FZD7) depends on the FZD7/ β‐catenin /Tp63/GPX4 signaling pathway." (PMID 40821694, 2025).
ovarian carcinoma (continued). "For example, a study on ovarian cancer using CRISPR-Cas9 screening showed that deletion of the transcription factor PAX8 significantly enhanced the pro-ferroptosis effect of the GPX4 inhibitor RSL3, revealing PAX8 as a novel regulator of GPX4-dependent ferroptosis resistance in tumor cells." (PMID 40559667, 2025). "For instance, in the ovarian cancer-resistant cell line CAOV2R, downregulation of the transcriptional coactivator with PDZ-binding motif (TAZ) leads to increased expression and activity of GPX4, thereby enhancing cells resistance to ferroptosis and contributing to carboplatin resistance." (PMID 39045454, 2024). "Therefore, metabolic vulnerabilities are attacked using the synthetic lethality approach in ovarian cancer cells overexpressing xCT, rather than directly inhibiting xCT or GPX4." (PMID 37842240, 2023).
diabetes (48 papers, 2018 to 2026). "In the context of diabetes, GPX4 deficiency can exacerbate ferroptosis, potentially contributing to β‐cell dysfunction and other complications." (PMID 41524084, 2026). "This marks the first report establishing cardiac ferroptosis in the human heart and elucidating potential mechanisms underlying diabetes-induced impaired iron homeostasis, downregulated GPX4, and lipid peroxidation in human heart failure." (PMID 38824159, 2024). "The present study has identified a noteworthy association between diabetes and diminished expression of retinal GPX4." (PMID 38321393, 2024). "Research has shown that the Nrf2/GPX4 signaling pathway is highly associated to the process of healing damage caused by diabetes as well as mitochondria and ferroptosis." (PMID 39479645, 2024). "Consistent with decreased Nrf2 immunoexpression in islet cells in diabetes, a similar pattern has been demonstrated for GPX4, a membrane-associated member of the GPX family that is one of the major downstream target enzymes of Nrf2 activation." (PMID 37600723, 2023). "GPX4 levels decreased in the kidney specimens of patients with diabetes and were associated with ferroptosis in the kidney tubular cells." (PMID 35226829, 2022). "Western blot showed that diabetes caused the decreased expression of GPX4 in mouse kidneys, but Ferrostatin-1 treatment increased the expression of GPX4 in kidneys of db/db mice." (PMID 33679620, 2021). "Additionally, an association between these variants and other cardiometabolic diseases, including diabetes and obesity, has also been reported in other genomic studies, further underscoring the important role of GPx4 in maintaining cardiometabolic homeostasis." (PMID 35453406, 2022). "In an environment of high glucose, diabetic patients may lead to the occurrence of ferroptosis in tissues and organs through iron metabolism, GPX4 metabolism, lipid metabolism, and other pathways, thereby further causing the development of diabetes and its complications." (PMID 38076182, 2023). "Individual patient differences such as age, metabolic status such as diabetes, obesity, chronic inflammation levels, and medication history can significantly impact the GPX4/GSH antioxidant axis and iron homeostasis balance." (PMID 41602830, 2026). "In the context of diabetes, hyperglycemia and hyperlipidemia exacerbate renal oxidative stress and impair the antioxidant functions of GPX4 and NRF2, leading to an oxidative-redox imbalance and abnormal iron accumulation." (PMID 40926987, 2025). "We found that the levels of cardiac Gpx4 started to increase as early as 1 week but dropped back to the original level at 2 week of diabetes (p < 0.05)." (PMID 38647950, 2024). "Its pharmacological effects include improvement in the blood glucose levels, iron content, and lipid peroxide accumulation via activation of the system XC/glutathione peroxidase 4/factor-erythroid factor 2 system in patients with diabetes." (PMID 38718039, 2024). "Thirdly, the specific mechanism by which ferroptosis regulates visual pathway damage in diabetes, such as GPX4/xCT/SLC7A11 and NAD(P)H/FSP1/CoQ10 systems, needs to be further explored and verified in vitro." (PMID 39080199, 2024). "This includes investigating myocardial ferroptosis and assessing NAC treatment in animals with longer durations of diabetes, and mining the factors contributing to the reduction of GPX4 or Slc7a11 in the early stages of diabetes." (PMID 38647950, 2024). "Ferroptosis plays an important role in visual pathway damage in diabetes, and GPX4 regulates this process." (PMID 39080199, 2024). "Ori treatment also improved the wound expression of glutathione peroxidase 4 (GPX4) and angiogenesis markers, reversing the delayed wound healing caused by diabetes mellitus (DM)." (PMID 39479645, 2024). "In ferroptosis and diabetes, depleted GPX4 and GSH, increased iron, and enhanced lipid peroxidation are common characteristics." (PMID 37117222, 2023).
diabetes (continued). "In STZ-induced diabetic mice and db/db mice diabetes models, GPX4 protein expression in the DN group was also dramatically downregulated compared with the NC group." (PMID 35721535, 2022). "Namely, we have found that Fer-1 restored the GPX4 hepatic expression that was decreased in diabetes and abolished the diabetes-induced decrease in total GPX activity." (PMID 36012572, 2022). "In animal studies, the expression of xCT and GPX4 mRNA in diabetes mellitus (DM) biopsies was lower than in controls." (PMID 36466094, 2022). "In patients with diabetes, GPX4 can regulate the NF-κB signaling pathway in the context of ferroptosis." (PMID 36225311, 2022). "In this study, docking of alginate, a biologically active polysaccharide, was performed to gain a theoretical understanding of its possible interactions with key therapeutic enzymes (COX-1, α-amylase, BChE, SOD1, and GPX4) related to inflammation, diabetes, neurodegeneration, and oxidative stress." (PMID 41304964, 2025). "Similarly, osteocytes co-cultured with AGEs and LPS to mimic diabetic periodontitis conditions in vitro underwent ferroptosis, characterized by downregulation of GPX4 and SLC7A1133." (PMID 41390753, 2025). "This phenomenon could potentially contribute to the observed reduction in retinal GPX4 expression in the context of diabetes." (PMID 38321393, 2024). "Therefore, in addition to affecting apoptosis, the present study identified MAP4K4 as a crucial regulator of ferroptosis in diabetes, and this process involves the GPX4-dependent GSH/GSSG balance and the S-nitrosylation of Drp1." (PMID 38724987, 2024). "Taken together, polyphenols prevent ferroptosis by modulating GSH synthesis, iron intracellular transport, and upregulating the GPx4 antioxidant system, which could be beneficial for preventing the progression of diabetes and vascular complications." (PMID 36670985, 2023). "The downregulation of GPX4 expression, the clearance of lipid reactive oxygen species and an increase in mRNA levels are all key characteristics of ferroptosis and related indicators of diabetes and its complications." (PMID 36225311, 2022). "Interestingly, our immunohistochemical analysis additionally showed strong nuclear localization of GPX4 in the control group, which was decreased in diabetes and normalized by Fer-1 treatment." (PMID 36012572, 2022). "Likewise, GPx4 overexpression was found to reverse cardiomyopathy in mouse models of diabetes by preventing mitochondrial damage." (PMID 35453406, 2022). "Additionally, associations with CKD related pathologies, such as hypertension (GPX4, CYP11B2, ERCC4), cardiovascular disease, diabetes and cancer predisposition (ERCC2) were also observed." (PMID 31924810, 2020). "Furthermore, diabetes decreased myocardium Gpx4 and nuclear Nrf2 expression, increased the expression of downstream-related ferroptosis factors, and increased superoxide accumulation, demonstrating that ferroptosis is closely related to diabetic cardiomyopathy." (PMID 35909950, 2022). "Collectively, these findings establish the KLF10/GPX4 axis as a previously unrecognized regulator of diabetes-associated vascular ferroptosis and suggest that PTX may offer a promising therapeutic approach for limiting ferroptosis-driven vascular injury in diabetes." (PMID 41926082, 2026). "The expression of SLC7A11, GPX4, FSP1, FTH1, and FPN1 were suppressed, while TFR1 was elevated in the kidney injury induced by diabetes." (PMID 39630101, 2025). "Surprisingly, our results showed the same changes in the expression of GPX4 and xCT in heart tissue after the use of MCC950 to fight against diabetes in rats." (PMID 38987672, 2024).
diabetes (continued). "Secondly, regarding the immunological aspect of adipose tissue, the accumulation of iron often observed in diabetes can activate ferroptosis in M2 macrophages, T regulatory cells, and B lymphocytes by reducing the levels of NRF2 and GPx4." (PMID 39279996, 2024). "In diabetes, upregulated MAP4K4 dramatically interferes with mitochondrial morphology and function, inhibits GPX4 expression, and promotes endothelial ferroptosis by stimulating SNO-Drp1, ultimately promoting cardiac microvascular injury." (PMID 38724987, 2024). "Further studies confirmed that MAP4K4 promoted SNO-Drp1 at human C644 (mouse C650) by inhibiting glutathione peroxidase 4 (GPX4) expression, through which MAP4K4 stimulated endothelial ferroptosis in diabetes." (PMID 38724987, 2024). "Diabetes, in this context, downregulates ATF4 to reduce GPX4 expression and suppresses GSR to decrease GPX4 activity in the human heart." (PMID 38824159, 2024). "We observed that, along with the reduced Nrf2 activation in diabetes, there was also a decrease in the content of GSH and protein expression of xCT, GCLM, and GPX4 (seen as a decrease in overall tissue immunopositivity and protein content)." (PMID 36012572, 2022). "Furthermore, GPX4 downregulation in adipose tissue has been implicated in vagal nerve ferroptosis and autonomic dysfunction in diabetes, via suppression of the NRF2‐GPX4 axis." (PMID 41524084, 2026). "Our current findings show that under natural conditions of diabetes, especially before D5w, D1w as well as D2w exhibited no or little change in ferroptosis-related proteins such as Gpx4 and Slc7a11, while at D5w this change became pronounced." (PMID 38647950, 2024). "Moreover, resveratrol also upregulated the expression of GPX4 and SLC7A11 in osteocytes during diabetic periodontitis conditions in vitro in the same fashion that ferrostatin-1 did." (PMID 37432277, 2023). "In diabetes, ROS production in the retina is significantly increased and further exacerbated by the collapse of antioxidant defensive system, including superoxide dismutase (SOD2) and glutathione peroxidase (GPX4)." (PMID 36092160, 2022). "In addition to GPX4, Fer-1 restored the activity of GST which showed a decreasing trend in diabetes." (PMID 36012572, 2022). "Furthermore, both obesity and diabetes are accompanied by significant increases in ROS and decreases in NRF2 and GPX4 levels, indicating a weakening of antioxidant capacity and activation of the ferroptosis process." (PMID 36479119, 2022). "However, compared to the earlier changes in Gpx4, significant downregulation of Slc7a11 did not occur until at week-5 of diabetes (p < 0.05)." (PMID 38647950, 2024). "Furthermore, a recent study showed that patients with diabetes exhibit significantly lower levels of GPX4 enzyme in their heart, than age-matched nondiabetic patients." (PMID 33558472, 2021). "Moreover, cryptochlorogenic acid (CCA) is an active compound in mulberry leaves, and CCA could inhibit ferroptosis by activating cystine/glutamate transporter (XC-)/GPX4/Nrf2 and inhibiting NCOA4 in diabetes, thereby reducing islet injury in the diabetic model." (PMID 38076182, 2023).
osteosarcoma (46 papers, 2020 to 2025). A usually aggressive malignant bone-forming mesenchymal neoplasm, predominantly affecting adolescents and young adults. "In MG63 osteosarcoma cells, decreased GPX4 expression is also associated with the progression of ferroptosis." (PMID 40002376, 2025). "Measurements of ferroptosis-associated proteins in osteosarcoma cells indicate that compared with normal cells, drug-resistant cells exhibit elevated GPX4 levels." (PMID 40740786, 2025). "By blocking the STAT3/Nrf2/GPX4 signaling pathway, osteosarcoma cells become more susceptible to cisplatin." (PMID 37576601, 2023). "GPX4 was reported to be associated with osteosarcoma progression and bone marrow development." (PMID 38686488, 2024). "In contrast, miR-1287–5p inhibited tumor development in osteosarcoma cells by downregulating GPX4 and inducing ferroptosis." (PMID 40403492, 2025). "Mechanistically, CUR triggered ferroptosis in osteosarcoma cells by regulation of the Nrf2/GPX4 signaling pathway." (PMID 40552277, 2025). "For example, telaprevir downregulates SLC7A11 and GPX4 expression, thereby inducing ferroptosis in osteosarcoma cells." (PMID 39812923, 2025). "Immunofluorescence staining showed that higher B1 doses led to decreased levels of SCD and GPX4 in osteosarcoma tissues, while reactive oxygen species (ROS) and lipid peroxidation levels increased in a dose-dependent manner." (PMID 41267108, 2025). "For instance, curcumin can induce ferroptosis and apoptosis in osteosarcoma cells through its ability to modulate the NRF2/GPX4 pathway." (PMID 39573995, 2024). "Researchers currently know that osteosarcoma, osteoporosis, and other orthopedic disorders are caused by NRF2, GPX4, and other ferroptosis star proteins." (PMID 39712490, 2024). "Further proof of ferroptosis induction by impairing STAT3/NRF2/GPX4 signaling is observed in osteosarcoma cells, where STAT3 inhibitors reactivated ferroptosis and increased cisplatin sensitivity." (PMID 38341410, 2024). "In osteosarcoma, high expression of GPX4 allows it to avoid ferroptosis, increasing its chances of surviving." (PMID 38800967, 2024). "Telocinobufagin blocks STAT3 signaling in non-small-cell lung cancer and osteosarcoma, while bufotalin induces ferroptosis by GPX4 degradation, thus inhibiting non-small-cell lung cancer progression." (PMID 39770538, 2024). "After the addition of the STAT3 inhibitor BP-1-102, the expression levels of Nrf2 and GPX4 in cisplatin-resistant osteosarcoma cells were significantly reduced." (PMID 38469234, 2024). "Mechanistically, OTULIN maintains the stability of the GPX4 protein by regulating the ubiquitination level of GPX4, thereby conferring resistance to cisplatin in osteosarcoma cells." (PMID 39721999, 2024). "Ferroptosis is involved tumor drug resistance by impairing STAT3/Nrf2/GPX4 signaling, and it increases the sensitivity of osteosarcoma cells to cisplatin." (PMID 36899330, 2023). "MiR-1287-5p inhibited the activity of GPX4 via binding to its 3′-untranslated region, hence inducing ferroptosis in osteosarcoma cells." (PMID 36819098, 2023). "For instance, bavachin induces ferroptosis in osteosarcoma cells by down-regulating STAT3 and GPX4, and increasing intracellular Fe2+ levels, thereby exerting anti-tumor effects on osteosarcoma." (PMID 36814203, 2023). "They further constructed an ACSL4/GPX4 double-gene knockout (ACSL4−/−/GPX4−/−) human osteosarcoma cell line U2OS." (PMID 36160012, 2022). "Ultrasound-activatable doxorubicin (DOX)-Fe(VI)@HMS-HE-PEG (DFHHP) nanoparticles synergistically boosted the growth suppression of hypoxic osteosarcoma by inducing ferroptosis with notable GPX4 downregulation." (PMID 35402247, 2022).